GPX4 (glutathione peroxidase 4)
Description:
Essential antioxidant peroxidase that directly reduces phospholipid hydroperoxide even if they are incorporated in membranes and lipoproteins. Can also reduce cholesterol hydroperoxide and thymine hydroperoxide (By similarity). Plays a key role in protecting cells from oxidative damage by preventing membrane lipid peroxidation. Required to prevent cells from ferroptosis, a non-apoptotic cell death resulting from an iron-dependent accumulation of lipid reactive oxygen species. The presence of selenocysteine (Sec) versus Cys at the active site is essential for life: it provides resistance to overoxidation and prevents cells against ferroptosis (By similarity). The presence of Sec at the active site is also essential for the survival of a specific type of parvalbumin-positive interneurons, thereby preventing against fatal epileptic seizures (By similarity). May be required to protect cells from the toxicity of ingested lipid hydroperoxides (By similarity). Required for normal sperm development and male fertility (By similarity). Essential for maturation and survival of photoreceptor cells (By similarity). Plays a role in a primary T-cell response to viral and parasitic infection by protecting T-cells from ferroptosis and by supporting T-cell expansion (By similarity). Plays a role of glutathione peroxidase in platelets in the arachidonic acid metabolism. Reduces hydroperoxy ester lipids formed by a 15-lipoxygenase that may play a role as down-regulator of the cellular 15-lipoxygenase pathway (By similarity). Can reduce fatty acid-derived hydroperoxides. Can also reduce small soluble hydroperoxides such as H2O2, cumene hydroperoxide and tert-butyl hydroperoxide.
Synonyms: PHGPx; GPx-4; GSHPx-4; MCSP; SMDS; snGPx; snPHGPx
Tractability: Small molecule: a structure with a bound ligand is known; a high-quality ligand is known. PROTAC: ubiquitination databases record sites on it; its protein half-life has been measured; a small molecule that binds it is known.
Target class: Enzyme; Oxidoreductase
Chemical probes: GPX4-IN-5, ML 210, RSL3
Gene: Protein-coding gene on chromosome 19 (1,103,982 to 1,106,791, forward strand). Ensembl gene ENSG00000167468.
Subcellular location: Mitochondrion (Isoform Mitochondrial); Cytoplasm (Isoform Cytoplasmic)
Subcellular location (Human Protein Atlas): Mitochondria; Nucleoplasm
Pathways (Reactome):
Metabolism: Biosynthesis of D-series resolvins; Biosynthesis of E-series 18(R)-resolvins; Biosynthesis of E-series 18(S)-resolvins; Biosynthesis of aspirin-triggered D-series resolvins; Synthesis of 12-eicosatetraenoic acid derivatives; Synthesis of 15-eicosatetraenoic acid derivatives; Synthesis of 5-eicosatetraenoic acids
Gene Ontology:
Molecular function: glutathione peroxidase activity; identical protein binding; phospholipid-hydroperoxide glutathione peroxidase activity; protein binding; peroxidase activity; selenium binding
Biological process: arachidonate metabolic process; lipoxygenase pathway; negative regulation of ferroptosis; protein polymerization; cellular response to oxidative stress; long-chain fatty acid biosynthetic process; phospholipid metabolic process; response to oxidative stress; spermatogenesis; cellular oxidant detoxification; response to estradiol
Cellular component: cytoplasm; cytosol; extracellular exosome; mitochondrion; nucleus; protein-containing complex; nuclear envelope
Genetic constraint (gnomAD): Loss-of-function variants: 28 observed, 27.72 expected, observed/expected ratio (o/e) 1.01, 90% interval 0.75 to 1.38. The synonymous counts are far from expectation, so gnomAD's model fits this gene poorly and the ratio says little. Missense variants: 357 observed, 278.6 expected, observed/expected ratio (o/e) 1.28, 90% interval 1.17 to 1.4. Synonymous variants: 163 observed, 109.63 expected, observed/expected ratio (o/e) 1.49, 90% interval 1.31 to 1.69.
Homologues: Orthologues: macaque GPX4 (99% identical), mouse Gpx4 (93% identical), dog GPX4 (91% identical), guinea pig GPX4 (91% identical), rat Gpx4 (91% identical), chimpanzee GPX4 (88% identical), pig GPX4 (72% identical), zebrafish gpx4b (62% identical), Caenorhabditis elegans gpx-6 (38% identical), Caenorhabditis elegans gpx-7 (37% identical). Paralogues in human: GPX7 (34% identical), GPX1 (32% identical), GPX3 (31% identical), GPX8 (30% identical), GPX2 (29% identical), GPX5 (28% identical), GPX6 (27% identical).
Diseases named in the same sentence as GPX4 in open-access papers:
GPX4 is named in the same sentence as 451 diseases in open-access papers, as found by Europe PMC text mining. Sharing a sentence is not in itself a finding about the gene and the disease. The quoted sentences say what the papers report.
breast carcinoma (191 papers, 2009 to 2026). "In contrast, loss of GPX4 function results in selective ferroptotic death of drug-tolerant persister cells and prevents tumor relapse in vivo, as demonstrated in breast cancer, non-small cell lung cancer, and ovarian cancer models." (PMID 41226317, 2025). "Consistent with our results, GPX4 dependency of DTP cells induced by targeted TKI has also been found in HER2‐amplified breast cancer, EGFR‐mutated NSCLC, and BRAF‐mutated melanoma." (PMID 39369284, 2025). "Overexpression of GPX4 has been linked to chemoresistance and a poor prognosis in cancers including nasopharyngeal carcinoma, breast cancer, and lung cancer." (PMID 40969276, 2025). "It was found that GPX4 is highly expressed in breast cancer tissues and its high expression is closely associated with poor prognosis of breast cancer patients." (PMID 38244591, 2024). "(1S,3R)‐RSL3 (50 nM) suppresses GPX4 activity in human COH‐BR1 breast cancer cells that overexpress GPX4 (L7G4 variant)." (PMID 36658724, 2023). "(1S,3R)-RSL3 can inhibit the peroxidase activity of GPX4 in BC (breast cancer) cells, causing the accumulation of peroxides and then ferroptosis." (PMID 37760042, 2023). "DT significantly increases MDA levels and decreases GPX4 activity in breast cancer cells, causing ferroptosis via lipid peroxidation." (PMID 36355532, 2022). "Long-term exposure to the cholesterol metabolite 27-hydroxycholesterol (27HC) causes breast cancer cells to be resistant to 27HC and overexpress GPX4, which inhibits ferroptosis and increases tumorigenicity and tumor metastasis." (PMID 36467032, 2022). "They identified two single nucleotide polymorphisms (SNPs) in GPX4 (rs713041 and rs757229) associated with all-cause mortality, linking the variations in GPX4 to the prognosis of breast cancer." (PMID 33292585, 2020). "GPx4 rs713041 were found to be associated with breast cancer mortality, the risk of colorectal cancer and cerebral stroke." (PMID 28499373, 2017). "The variant T allele for GPX4 rs713041 SNP was associated with increased risk of mortality by breast cancer and decreased eGPx activity." (PMID 27164132, 2016). "Gpx4 has also been reported to be associated with multiple types of cancers, including breast cancer, colorectal cancer, and aggressive prostate cancer; however, no study has presented its correlation with HCC." (PMID 24633177, 2014). "This is in agreement with study by Udler and colleagues, where they reported that GPX4 rs757229 and rs713041 were associated with a greater risk of all-cause mortality after diagnosis with breast cancer." (PMID 24278290, 2013). "GPX4 was significantly associated with better breast cancer survival among those with the highest NA ancestry (PARTP = 0.05)." (PMID 24278290, 2013). "Previously genotype for rs713041 (GPX4) has been reported to be associated with prognosis after diagnosis of breast cancer." (PMID 24039907, 2013). "GPX4 was significantly associated with breast cancer survival among those with the highest NA ancestry (PARTP = 0.05) only." (PMID 24278290, 2013). "Moreover, DMOCPTL, a derivative of the natural product parthenolide, induces the apoptosis and ferroptosis of breast cancer cells by directly binding to GPX4 and causing degradation of GPX4." (PMID 38892270, 2024). "Moreover, it elicits an increase in lipid peroxide levels, downregulates the expression of ferroptosis-associated proteins GPX4 and xCT, and induces ferroptosis in breast cancer cells." (PMID 39399463, 2024). "Interestingly, GEPs induced by different concentrations of ORes were significantly enriched in the PI3K-AKT signalling pathway downstream of EGFR, and activation of the EGFR/PI3K/AKT/GPX4 axis was associated with poor prognosis in breast cancer patients." (PMID 39881871, 2024).
breast carcinoma (continued). "This may be due to the relative deficiency of energy metabolism and oxygen metabolism in breast cancer tissues with overgrowth of cancer cells, causing low expression of the compensatory GPX4 inhibitory system as well as high levels of ferroptosis." (PMID 38413708, 2024). "For example, genes such as acyl-CoA synthetase long-chain family member 4 (ACSL4) and GPX4 have been shown to serve as independent predictors of chemosensitivity in neoadjuvant chemotherapy for breast cancer, and their expression levels are strongly associated with patient prognosis." (PMID 39759144, 2024). "Additionally, loss of GPX4 function resulted in lapatinib-resistant breast cancer cell ferroptosis in vitro and prevented tumor relapse in vivo." (PMID 38742521, 2024). "This in turn would suggest that claudin-low breast cancers may be susceptible to GPX4 inhibition, should clinical GPX4 inhibitors become available." (PMID 35523770, 2022). "Since the GPX4 rs713041 SNP is associated with mortality of breast cancer patients and the risk of colorectal cancer, the CC allele of GPX4 rs713041 SNP may increase the survival of cancer cells or ectopic endometrium by against the oxidative stress." (PMID 32679649, 2020). "In addition, impaired GPx4 expression in peripheral blood monocytes was shown to be a biomarker of increased risk of breast cancer." (PMID 32571353, 2020). "At a low selenium intake, SNPs at this region may influence the susceptibility to disease GPX4 SNP (rs713041) had been demonstrated in previous studies to be associated with an increased risk of death in breast cancer patients." (PMID 32679649, 2020). "GPx4 rs2074451 variant was also found to be associated with breast cancer survival." (PMID 28499373, 2017). "Notably, GPX4 rs2074451 showed marginally significant interaction with NA ancestry and having a T allele was associated with decreased likelihood of dying from breast cancer among women with >28% NA ancestry." (PMID 24278290, 2013). "However, no genetic association study of genotype for either rs713041 (GPX4) or for any SNPs in SEPP1 and BC risk has been carried out so far, although lymphocyte GPx4 mRNA expression was found to be lower in breast cancer patients than controls." (PMID 24039907, 2013). "Additionally, previous studies have shown that impaired expression of the GPX4 gene in the PBMCs of breast cancer patients serves as a biomarker for an increased risk of breast cancer, further suggesting the association between GPX4 expression in PBMCs and disease." (PMID 39119475, 2024). "Some key indicators of ferroptosis, such as acyl-CoA synthetase long-chain family 4 (ACSL4) and GPX4, their individual expression, and their combined status were independent prognostic factors for disease-free survival, demonstrating the diagnostic value of ferroptosis genes in breast cancer." (PMID 37928550, 2023). "Since ACSL4 is expressed higher in breast cancer compared to the adjacent normal tissue, and PUFAs are targets of lipid peroxidation, cancer cells might be more susceptible to lipid peroxidation and ferroptosis, thus GPX4 is more essential in cancer cells." (PMID 33672555, 2021). "Co-targeting FSP1 and GPX4 therefore represents a rational strategy to overcome ferroptosis resistance in MCF-7-like breast cancers." (PMID 41750619, 2026). "The lysine acetyltransferase 5 (KAT5) inhibitor ketamine reduces H3K27ac levels in the GPX4 promoter region, which boosts ferroptosis from breast cancer." (PMID 40327848, 2025). "Previous studies suggested that the RUNX1 intronic transcript (RUNX1-IT1) can inhibit ferroptosis in breast cancer cells by stabilizing GPX4 mRNA." (PMID 41573542, 2025). "A published report has shown that the NF-κB member, RelB, plays a role in upregulating GPX4 expression and suppressing ferroptosis, thereby increasing the resistance of ER+ breast cancer cells to Tamoxifen." (PMID 39833180, 2025).
breast carcinoma (continued). "Acts as a GPX4-targeting ferroptosis inducer, offering mechanistic insight transferable to breast cancer contexts." (PMID 41008615, 2025). "It emphasizes the sensitivity of different breast cancer subtypes to ferroptosis as a driving force in the current research landscape and highlights the pivotal role of GPX4 in the regulatory mechanisms of ferroptosis in breast cancer as a key focus." (PMID 40009842, 2025). "Ultimately, the GPX4 protein is a novel target for breast cancer therapy, particularly TNBC, and it offers a novel strategy for TNBC treatment by reducing GPX4 expression and inducing ferroptosis." (PMID 40969276, 2025). "A significant increase in GPX4 expression in lung cancer and a decrease in breast cancer was observed, which was consistent with the transcriptional data." (PMID 41142608, 2025). "GPX4 expression is significantly elevated in various tumors, including breast cancer 7, colorectal cancer 8, lung cancer 9, and liver cancer." (PMID 40365295, 2025). "BRCA1 deficiency induces ferroptosis vulnerability to PARP and GPX4 co-inhibition, which is useful for therapeutic strategies to overcome PARP inhibitor resistance in BRCA1-deficient cancers, including breast cancer." (PMID 39858464, 2025). "In an in vivo model, using tumors xenograft with breast cancer cell lines in mouse, GPX4 inhibitors plus anti-PD-1-antibody significantly inhibited tumor growth compared with therapy with anti-PD-1 therapy alone." (PMID 41339932, 2025). "For example, RelB-mediated GPX4 upregulation facilitates tamoxifen resistance in breast cancer, while GPX4 inactivation induces ferroptosis and augments chemotherapy sensitivity." (PMID 39935430, 2025). "It has been reported that RUNX1 intron transcript 1 (RUNX1-it1) is significantly overexpressed in breast cancer tissues, and it can block the impact of ferroptosis by increasing GPX4 expression, thereby promoting the occurrence of breast cancer." (PMID 40009842, 2025). "Since ERα transcriptionally upregulated SLC7A11 and SLC3A2 expression, we believe that estrogen/ERα inhibits ferroptosis mainly through the xc−-GPX4 axis in ER+ breast cancer." (PMID 39833180, 2025). "For example, oxidized resveratrol (ORes) significantly inhibited the proliferation and growth of breast cancer cells by inducing ferroptosis through inhibition of the EGFR/PI3K/AKT/GPX4 signaling axis." (PMID 40416989, 2025). "METTL3 can also target GPX4 by introducing m6A modification on its mRNA, increasing its mRNA stability in breast cancer and showing a pivotal role in anti-ferroptotic mechanism in that context." (PMID 41339932, 2025). "Induces ferroptosis via GPX4 inhibition, providing a mechanistic template relevant to breast cancer." (PMID 41008615, 2025). "Conversely, a recent study revealed that ferroptosis induced by pharmaceutical inhibition of GPX4 increased when breast cancer cells were co-cultured with RAW 264.7 macrophages." (PMID 41326365, 2025). "Since the combination of overexpressing SLC7A11 and SLC3A2 partially alleviated ferroptosis induced by ERα knockdown, it is also possible that estrogen/ ERα regulates ferroptosis through xc−-GPX4 independent pathway in ER+ breast cancer cells." (PMID 39833180, 2025). "Keyword analysis highlights the maturity of glutathione peroxidase 4-related research, with breast cancer subtypes emerging as motor themes and the tumor microenvironment, immunotherapy, and prognostic models identified as basic themes." (PMID 40009842, 2025). "In breast cancer, a decreased level of GPX4, a critical factor that regulates the oxidation of glutathione, prevents lipid peroxide formation as well as ferroptosis." (PMID 39858015, 2025). "While GPX4 is an important regulator of metastatic progression of breast cancer and adaptive response to lipid accumulation, the role of GPX4 in obesity-related TNBC progression has not yet been reported." (PMID 40001204, 2025).